TTR (transthyretin)
Diseases named in the same sentence as TTR in open-access papers (continued):
Sharing a sentence is not in itself a finding about the gene and the disease.
amyloidosis (continued). "In this case, patisiran accelerated the degradation of normal or mutated transthyretin (TTR) that caused TTR amyloidosis." (PMID 36561087, 2022). "Recent studies have clearly shown that CA, particularly transthyretin-related amyloidosis (ATTR), is a leading cause of heart failure (HF), affecting approximately 15% of subjects with HF with preserved ejection fraction (HFpEF)." (PMID 36359408, 2022). "The ATTR amyloidosis derived from a transthyretin variant is the most common hereditary amyloidosis in the world." (PMID 35898389, 2022). "TTR amyloidosis incorporates two subtypes: ATTRv (variant or hereditary amyloidosis) stands for all hereditary forms, whereas ATTRwt (wild-type amyloidosis) is defined by sporadic mutations of the transthyretin gene." (PMID 35453653, 2022). "In the NCT04601051 trial, a single dose of NTLA‐2001 is intravenously administered to treat hereditary transthyretin (TTR) amyloidosis by editing the mutated TTR gene." (PMID 37323878, 2022). "ATTR-mediated amyloidosis is a condition caused by a buildup of TTR either caused by mutations in the TTR gene." (PMID 35269876, 2022). "Hereditary transthyretin (ATTRv) amyloidosis is a severe, progressive, and heterogeneous multisystemic condition due to mutations in the TTR gene." (PMID 36552168, 2022). "Mutations in genes related to amyloidosis were found in 15% (n = 22) of patients, being: transthyretin (TTR) (59%; n = 13); fibrinogen (27%; n = 6); and Mediterranean Fever (MEFV) gene (14%; n = 3)." (PMID 36471404, 2022). "It has been reported that fibrils formed by proteolytic fragments are most often found in old patients with sATTR, suggesting that age-associated alteration of TTR proteolysis is a risk factor for amyloidosis." (PMID 36614141, 2022). "Transthyretin mutations result in amyloidosis,hence siRNA targeting the synthesis of this protein can lower the rate of itsproduction." (PMID 39076655, 2022). "In individuals with a phenotype suspicious for amyloidosis such as hypertrophic cardiomyopathy, the presence of a TTR mutation has diagnostic implications and points away from a myocardial sarcomeric disease and towards amyloidosis." (PMID 34380564, 2021). "Pathogenic or likely pathogenic (P/LP) variants in the transthyretin (TTR) gene are one cause of transthyretin amyloidosis, and genomic screening has been proposed to identify at-risk individuals." (PMID 34746851, 2021). "Monomer dissociation and subsequent misfolding of the transthyretin (TTR) is one of the most critical causative factors of TTR amyloidosis." (PMID 34746240, 2021). "In all forms of amyloidosis, the kinetics of amyloid deposition depend on the supply of the respective amyloid precursor protein, and very high-level expression of TTR in line N4 mice here was associated with the most abundant amyloid deposition." (PMID 34876572, 2021). "Amyloid transthyretin (ATTR) amyloidosis is a potentially life-threatening cause of heart failure caused by accumulation of liver-derived, misfolded transthyretin." (PMID 34331215, 2021). "Hereditary transthyretin (ATTRv) amyloidosis is a rare, progressive, multisystemic, and fatal form of amyloidosis caused by extracellular deposition of transthyretin amyloid fibrils primarily synthesized by the liver." (PMID 33430941, 2021). "Recently, cardiac transthyretin (TTR) amyloidosis is becoming recognized as one of major causes of underdiagnosed HF." (PMID 33679409, 2021). "The formation of TTR amyloid deposits of different morphologies underlies the pathogenesis of severe and potentially lethal diseases, i.e., amyloidoses." (PMID 34359938, 2021). "Hereditary transthyretin (TTR) amyloidosis (ATTRv) is an autosomal dominant, systemic disease transmitted by amyloidogenic mutations in the TTR gene." (PMID 34719408, 2021). "TTR, an etiologic agent associated with aggregation of misfolded proteins and amyloidoses, was highly expressed in aged α-cells, consistent with that in islet cells of type 2 diabetic individuals." (PMID 34691567, 2021).
amyloidosis (continued). "Whereas wild-type ATTR amyloidosis is a disorder of older people, many point mutations in the TTR gene are associated with dominantly inherited susceptibility to forms of the disease that can develop at any time from early adult life onwards." (PMID 34876572, 2021). "Thyroxine (TTR) amyloidosis is caused by the TTR gene mutation and characterized by excessive deposition of thyroxine in the myocardium." (PMID 33935716, 2021). "A TTR variant alone cannot confirm a diagnosis of ATTRv amyloidosis because of incomplete penetrance in carriers." (PMID 31907599, 2021). "ATTR-ACT is a phase III multicenter double-blinded study assessing 441 patients of cardiac amyloidosis, 106 with ATTRm (familial transthyretin-associated forms of amyloid) and 335 with ATTRwt (wild-type transthyretin-associated forms of amyloid)." (PMID 34703707, 2021). "Hereditary transthyretin-mediated amyloidosis is a condition with adult onset caused by mutation of transthyretin and characterized by extracellular deposition of amyloid and destruction of the somatic and autonomic PNS." (PMID 34646114, 2021). "The availability of multidisciplinary care for patients with or at risk for amyloidosis at MSHS further supported the inclusion of TTR in the program." (PMID 33546753, 2021). "ATTR amyloidosis is the most common familial form of amyloidosis and is caused mainly by non-synonymous mutations in the transthyretin gene (TTR; Chr." (PMID 33459839, 2021). "Variants in the TTR gene causing ATTRm amyloidosis are relatively rare but are endemic in some geographic regions (e.g., Portugal and Sweden)." (PMID 34062949, 2021). "Hereditary amyloid transthyretin (ATTRv; v for “variant”) amyloidosis with polyneuropathy (PN) is a rare multisystemic disease with predominant involvement of the peripheral nervous system and amyloid deposits in the endoneurium." (PMID 31907599, 2021). "So far, over 150 mutations in the primary sequence of TTR have been identified, most of which are associated with amyloidosis." (PMID 34093538, 2021). "The identification of potentially pathogenic TTR mutations has important clinical implications for the classification, diagnosis, and treatment of amyloidosis." (PMID 34380564, 2021). "To date, more than 100 mutations have been described in the TTR gene, although most ATTRv amyloidoses are caused by p.Val142Ile (also known as Val122Ile) and p.Val50Met (also known as Val30Met) mutations." (PMID 33459839, 2021). "The mainstay of treatment is symptomatic care of heart failure, which is more beneficial in patients with ATTRm (familial transthyretin-associated) and ATTRwt (wild-type transthyretin-associated) amyloidosis." (PMID 34703707, 2021). "Type II amyloidosis is caused by the deposition of transthyretin (TTR), which will be the main focus of this article." (PMID 34017661, 2021). "Hereditary transthyretin-mediated (hATTR) amyloidosis, also known as ATTRv (v for variant) amyloidosis, is an underdiagnosed, progressively debilitating, and fatal disease caused by mutations in the transthyretin (TTR) gene." (PMID 34079032, 2021). "The data described in this manuscript suggest that there are TTR variants potentially associated with amyloidosis in Saudi Arabia and highlight the need for further clinical data regarding this patient population." (PMID 34380564, 2021). "Recently, the feasibility of treating genetic diseases caused by single-gene mutations was established in a Phase 1 trial for transthyretin amyloidosis, a disease caused by the accumulation of misfolded transthyretin (TTR)." (PMID 34445274, 2021). "The most common form of hereditary amyloidosis results from a mutation of the TTR gene inherited in an autosomal dominant manner." (PMID 34106429, 2021). "Transthyretin (TTR) amyloidosis is a systemic disease caused by dissociation of the TTR tetramer and subsequent fibril deposition in tissues." (PMID 34719408, 2021).
amyloidosis (continued). "Hereditary transthyretin (TTR) amyloidosis (ATTRv) is a heterogeneous disease with a clinical presentation that varies according to geographical area and TTR mutation." (PMID 34112225, 2021). "Amyloid transthyretin (ATTR) amyloidosis is caused by tissue deposition of full‐length and fragmented monomers of transthyretin (TTR), a tetrameric protein synthesized by the liver acting as a carrier for thyroxine (T4) and retinol‐binding protein." (PMID 33982288, 2021). "The two common types are wild-type transthyretin (ATTRwt) and variant amyloidogenic (ATTRv) amyloidosis." (PMID 34575344, 2021). "Following this 'silent revolution', in 2018 the US Food and Drug Administration approved the first RNAi therapeutic, a treatment for polyneuropathy caused by transthyretin (TTR) amyloidosis, from Alnylam Pharmaceuticals18." (PMID 33893357, 2021). "ATTR is a heterogeneous disease that can be divided into a hereditary form caused by mutations in the transthyretin-gene (ATTRv) and wild-type transthyretin amyloidosis (ATTRwt)—previously designated senile systemic amyloidosis." (PMID 33367948, 2021). "HA includes Hereditary amyloidogenic transthyretin (hATTRv), amyloidosis derived from a fibrinogen variant (AFib), that is the most frequent HA in Northern Europe, variants of apolipoproteins (AI, AII, C-II, CIII), gelsolin (AGel), and lysozyme (ALys)." (PMID 33801069, 2021). "Fourteen percent (7 of 49) of individuals aged ≥60 or older with a P/LP TTR variant had heart disease and ventricular septal thickness >1.2 cm, only one of whom was diagnosed with amyloidosis." (PMID 34746851, 2021). "Hereditary transthyretin-mediated (hATTR) amyloidosis is an underdiagnosed, progressively debilitating disease caused by mutations in the transthyretin (TTR) gene." (PMID 34079032, 2021). "More than 130 mutations within the TTR gene have been associated with autosomal dominant familial forms of amyloidosis, which typically present earlier onset and are often severe." (PMID 34343569, 2021). "The indication for these drugs is hereditary transthyretin-mediated amyloidosis, in which the TTR protein destabilized by mutations is deposited extracellularly as fibrillar insoluble amyloids, causing organ dysfunction." (PMID 34638486, 2021). "Patients with ATTR-CM or ATTRv amyloidosis due to the p.V142I (ATTRV122I) TTR mutation or other TTR variant cardiomyopathies will likely be significantly affected by COVID-19, perhaps disproportionately so." (PMID 33957949, 2021). "In particular, the mutant and wild type TTR amyloidoses are human disorders caused by TTR misfolding, native tetrameric structure lost, and insoluble aggregate formation and deposition in different organs." (PMID 33919289, 2021). "The three most common forms are amyloid light chain (AL) amyloidosis associated with plasma cell dyscrasias, amyloid A (AA) amyloidosis in chronic inflammatory disorders, and transthyretin (TTR) amyloidosis." (PMID 34440326, 2021). "Among them, transthyretin (TTR) amyloidosis is the most common form of hereditary autosomic dominant systemic amyloidosis, in which TTR point mutations result in deposition of amyloidogenic species in different tissues." (PMID 34093538, 2021). "Amyloid transthyretin (ATTR) amyloidosis is caused by the systemic deposition of transthyretin molecules, either normal (wild‐type ATTR, ATTRwt) or mutated (variant ATTR, ATTRv)." (PMID 33982288, 2021). "Mutations in TTR, associated with amyloidosis, create tetrameric instability leading to dissociation into monomers." (PMID 34429155, 2021). "All forms of TTR, including wild type, can cause amyloidosis and the propensity for amyloidosis in people with wild type TTR is just as heritable as it is for those with a mutant form." (PMID 33203794, 2020). "Amyloidosis caused by wild-type TTR follows the same mechanism as amyloidosis caused by variants of TTR and thus should be considered as variants of the same disease for purposes of clinical studies." (PMID 33203794, 2020).
amyloidosis (continued). "A recent research breakthrough on lipid NPs encapsulating siRNA was the 21 base pairs siRNA drug patisiran to treat TTR amyloidosis, a multisystemic disease causes by misfolded TTR, that affects nerves, heart, and the gastrointestinal tract." (PMID 33195435, 2020). "Revusiran was in development as a potential treatment for hereditary transthyretin-mediated amyloidosis (hATTR amyloidosis), a rare, life-threatening, autosomal dominant multi-systemic disease caused by mutations in the TTR gene." (PMID 31821125, 2020). "Mutations in TTR are associated with hereditary forms of TTR amyloidosis and the most frequent TTR variant is V30M that causes ATTRV30M amyloidosis, also known as familial amyloid polyneuropathy (FAP)." (PMID 32197355, 2020). "Mutated TTR genes cause hereditary transthyretin-mediated amyloidosis, a rare neurodegenerative disease leading to paresthesia, muscular weakness and autonomic dysfunction evoked by deposition of abnormal transthyretin in the peripheral nervous system." (PMID 33339365, 2020). "In Sweden, we normally require demonstration of amyloid deposits in a tissue biopsy to establish the diagnosis of ATTR amyloidosis, even in patients with a proven TTR mutation and typical symptoms of amyloidosis." (PMID 33032630, 2020). "TTR amyloidosis encompasses both familial (mutant) TTR and wild-type TTR, whereas AL amyloidosis is usually associated with an underlying plasma cell dyscrasia." (PMID 33195479, 2020). "Hereditary transthyretin (TTR) amyloidosis (hATTR) is a rare life-threatening disorder caused by amyloidogenic coding mutations located in TTR gene." (PMID 33203445, 2020). "Mutations in the gene coding for TTR were evolutionarily selected to enhance its role as a transporter of thyroxine and retinol, but play an important role in amyloidosis." (PMID 33203794, 2020). "Inotersen, an antisense oligonucleotide which reduces circulating TTR levels, is approved in the USA and EU for the treatment of the polyneuropathy associated with hATTR amyloidosis." (PMID 32641071, 2020). "Among these is transthyretin (TTR), which causes wild-type TTR amyloidosis (wtATTR; also called senile systemic amyloidosis, SSA) The development of amyloid in this disease is likely promoted by age-related, post-translational modifications of the TTR protein." (PMID 32604774, 2020). "In both variants of amyloidosis, i.e. the immunoglobulin light chain (AL) and transthyretin (ATTR) amyloidosis, protein deposition can culminate in infiltrative disease processes that affect the heart." (PMID 33304689, 2020). "For instance, the protein transthyretin (TTR) forms a functional tetramer but can aggregate into insoluble deposits in TTR amyloidosis, causing neuropathy and cardiomyopathy." (PMID 33276458, 2020). "One recent study showed that NT-proBNP is a biomarker that can be highly elevated in ATTRh amyloidosis, especially among asymptomatic carriers of a TTR gene mutation or patients with neurological symptoms only." (PMID 32328845, 2020). "Hereditary transthyretin-mediated (hATTR) amyloidosis is a progressive and life-threatening disease caused by mutations in the gene encoding the transthyretin (TTR) protein." (PMID 32641071, 2020). "Even though the use of miRNAs in a clinical setting is currently limited, the recent FDA approval of siRNA for the treatment of the peripheral nerve disease caused by hereditary transthyretin-mediated amyloidosis is promising for ncRNA therapy." (PMID 32353968, 2020). "Three general factors have been linked with certainty to the development of TTR amyloidosis: age, gender, and stability of the TTR tetramer." (PMID 33203794, 2020). "Four African American/African-descent participants were heterozygous for TTR rs76992529, a missense variant associated with amyloidogenic transthyretin amyloidosis." (PMID 31797629, 2020).
amyloidosis (continued). "One of the therapeutic strategies to ameliorate the progress of TTR-associated amyloidosis is the stabilization of the soluble tetrameric form of the protein to prevent aggregation and fibril formation." (PMID 33348885, 2020). "Another example where flanking regions protect from aggregation is the homo-tetrameric protein transthyretin (TTR), which is expressed in the liver and cerebrospinal fluid and is associated with amyloidosis." (PMID 33335475, 2020). "Second, it is well-known that wild-type transthyretin amyloidosis is an underdiagnosed cause of HFpEF." (PMID 33330670, 2020). "Ultimately, 132 patients had got a final diagnosis of amyloidosis, mainly ATTRv amyloidosis, and 53 had been considered as asymptomatic carriers of a TTR mutation." (PMID 33032630, 2020). "Hereditary transthyretin (hATTR) amyloidosis is a rare, systemic, progressive, debilitating, and fatal disease characterized by mutations in the gene encoding the transthyretin (TTR) protein." (PMID 31853709, 2020). "This phenomenon allows them to effectively deliver encapsulated siRNA into hepatocytes and silence a mutated version of the TTR gene, which was tested on patients suffering from hATTR amyloidosis." (PMID 33334048, 2020). "TTR amyloidosis is caused by dissociated monomers that are destabilized and refold into an amyloidogenic form." (PMID 33203794, 2020). "TTR tetramer is usually stable, exception when a single point mutation occurs and drastically decreases its stability, thus promoting amyloidosis." (PMID 32456156, 2020). "One of such LNP-mediated delivery systems, LNP-INT01, was used with CRISPR to repair the mutated Ttr gene that causes transthyretin (TTR)-mediated amyloidosis due to the accumulation of amyloid proteins." (PMID 30823430, 2019). "Among different TTR variants, there is also high variability of predominance of polyneuropathy or cardiomyopathy as main clinical manifestations in ATTRv amyloidosis." (PMID 30875761, 2019). "TTR misfolding and amyloid formation is associated with numerous amyloidoses including senile systemic amyloidosis, familial amyloidotic polyneuropathy, and familial amyloid cardiomyopathy." (PMID 30631096, 2019). "With the brand name of Onpattro, Patisiran is the only FDA-approved RNA interference (RNAi) drug targeting polyneuropathy caused by hereditary transthyretin-mediated amyloidosis (hATTR)." (PMID 31608113, 2019). "In mature adults, a late-onset acquired TTR amyloidosis also known as senile systemic amyloidosis (SSA) is caused by the accumulation of wild-type in organs." (PMID 30934952, 2019). "Direct MALDI revealed a highly significant correlation between measured and theoretical mass shifts from WT TTR in serum samples from ATTRv amyloidosis patients with different TTR mutations (r2 = 0.9969)." (PMID 31133063, 2019). "The year 2018 was a landmark year for RNAi with FDA approving Alnylam's ONPATTRO (Patisiran), the first drug to use this system to reduce transthyretin expression, which causes transthyretin-mediated amyloidosis in adults." (PMID 31850193, 2019). "In ATTRm amyloidosis, the rate of cardiac versus neurological involvement depends on the underlying TTR mutation of which over 100 have been identified." (PMID 31359320, 2019). "The diagnosis of ATTRv is challenging, often relying on genetic tools to identify TTR mutations as well as on the identification of Congo Red-positive amyloid deposits in biopsies usually taken from sural nerve and salivary glands." (PMID 31253122, 2019). "Transthyretin (TTR) amyloidosis is a life-threatening disease (Online Mendelian Inheritance in Man: #105210) caused by coding mutations in the TTR gene." (PMID 30813263, 2019). "The most common forms of systemic amyloid are AL amyloid seen in plasma cell dyscrasias, AA amyloid associated with inflammatory conditions, and TTR amyloidosis due to either familial gene mutation or wild type protein, formerly called senile amyloidosis." (PMID 31200733, 2019).